CCL11 (C-C motif chemokine ligand 11)
Diseases named in the same sentence as CCL11 in open-access papers (continued):
Sharing a sentence is not in itself a finding about the gene and the disease.
vitamin D (1 paper, 2013). "Increased expression of CCL19 mRNA was observed in the CD11c+ cells from male vitamin D-deficient mice, when compared to their vitamin D-replete counterparts, while vitamin D deficiency down-regulated the expression of mRNAs of CCL11, CCL19, CCL20 and CXCL1 in CD11c+ cells from female mice." (PMID 23826346, 2013).
vitiligo (1 paper, 2025). Generalized well circumscribed patches of leukoderma that are generally distributed over symmetric body locations and is due to autoimmune destruction of melanocytes. "Among the 11 inflammatory cytokines associated with CHD, vitiligo was found to be causally associated with one of them, namely CCL11 (OR = 0.9804, 95% CI 0.9637–0.9973, p = 0.023)." (PMID 40169829, 2025). "Specifically, vitiligo was negatively associated with CCL11 (OR = 0.9804, 95% CI 0.9637–0.9973, p = 0.023), which was in turn associated with an increased risk of CHD (OR = 1.0954, 95% CI 1.0344–1.1600, p = 0.002)." (PMID 40169829, 2025). "Combined, CCL11 negatively mediated the association between vitiligo and CHD, with a mediation proportion of −14.3% (95% CI −0.00369, −0.0000114, p = 0.0486)." (PMID 40169829, 2025). "We identified CCL11 as the potential mediator in the causal pathway from vitiligo to CHD." (PMID 40169829, 2025). "Taken together, these studies indicate that vitiligo may be indirectly associated with decreased CCL11 levels, as our findings suggested." (PMID 40169829, 2025). "CCL11 was identified to partially mediate the association between vitiligo and CHD." (PMID 40169829, 2025). "GO and GeneMANIA suggested that CCL11 may mediate the association between vitiligo and CHD through chemokine-related functions and pathways." (PMID 40169829, 2025). "In summary, our study identified the potential causal association between vitiligo and CHD, and highlighted the mediating effect of CCL11 in this association." (PMID 40169829, 2025). "Our study revealed the potential causal association between vitiligo and CHD, with CCL11 as a potential mediator." (PMID 40169829, 2025). "Meanwhile, our two-step mediation MR analysis found that the causal association between vitiligo and CHD was partially mediated by CCL11." (PMID 40169829, 2025). "Our study revealed the negative mediating role of CCL11 in the causal association between vitiligo and CHD." (PMID 40169829, 2025). "Therefore, the downregulation of CCL11 in vitiligo had a partial protective effect on the development of CHD." (PMID 40169829, 2025). "The inhibition or downregulation of CCL11 might be a potential therapeutic target for CHD in patients with vitiligo." (PMID 40169829, 2025). "As opposed to the positive total effect of vitiligo on the risk of CHD, CCL11 negatively mediated this association and attenuated the effect of vitiligo on CHD." (PMID 40169829, 2025). "There is limited direct evidence regarding the negative correlation between CCL11 and vitiligo." (PMID 40169829, 2025).
tumor (111 papers, 2007 to 2026). "CCL11, downregulated in CR at baseline, encodes a chemokine linked to Th2 inflammation and tumor progression through AKT and ERK pathway activation." (PMID 40659866, 2025). "The release of these secretory products through degranulation causes tumor cell death and this process can be enhanced by several soluble mediators, including IL-5, IL-33, CCL11 and IFN-γ." (PMID 40050933, 2025). "CCL11 encodes the major chemokine responsible for eosinophil recruitment and infiltration in the tumor microenvironment." (PMID 40428397, 2025). "Our work showed that mRNA vaccines encoding HPV-E6E7 fused with chemokine CCL11 treatment achieved durable complete remission in tumor animal models." (PMID 39203999, 2024). "CCL11 expression is associated with BRCA's clinical features such as tumor stage, grade, and molecular subtype." (PMID 38305920, 2024). "Conversely, tumor growth was markedly increased in Ccl11–/– mice, Il5–/–;Ccl11–/– and eosinophil-deficient mice." (PMID 33233582, 2020). "They found that an overexpression of CCL11 in the tumor was significantly associated with a poor overall survival." (PMID 28537901, 2017). "Thirdly, tumor-associated eosinophil infiltration may be mediated by chemoattractants that are released from necrotic neoplastic cells, with CCL11 potentially playing a significant role in this process." (PMID 40429807, 2025). "In IL-5/CCL11 knockout mice or eosinophil-deficient mice, tumor growth is significantly enhanced." (PMID 40721870, 2025). "Furthermore, CCL11-mediated tumor-associated macrophage (TAM) recruitment has been implicated in establishing immunosuppressive niches that facilitate tumor progression." (PMID 40429807, 2025). "Notably, diminished expression of CCL11 has been linked to increased tumor load and reduced eosinophil infiltration in preclinical mouse models." (PMID 40761780, 2025). "Recent investigations have identified CCL11 as a promising biomarker with dual utility—firstly, by detecting neoplastic processes through its association with tumor-associated inflammation, and secondly, in monitoring therapeutic responses via inflammation resolution tracking." (PMID 40429807, 2025). "Using gene expression analysis, we identified that CAFs overexpress Chemokine ligand 11 (CCL11), which is associated with tumor migration and invasion, increased expression of cancer stem cell properties, and induction of the epithelial-to-mesenchymal transition." (PMID 35804913, 2022). "CCL11 is a chemokine related to chronic inflammation and may take part in tumor-associated inflammation." (PMID 28537901, 2017). "Lower concentrations of CCL11 in the tumor tissue were associated with better prognosis." (PMID 28537901, 2017). "This might be caused by a CCL11-dependent activation of cell proliferation, tumor migration and invasion." (PMID 28537901, 2017). "Our findings unveil CCL11 as a master regulator of the pro-tumorigenic niche post-resection, driving recurrence through coordinated immune evasion and promoting tumor invasiveness." (PMID 41714328, 2026). "In orthotopic models, CCL11 enrichment increased tumor burden and extrahepatic metastases, while post-resection anti-CCL11 therapy reduced HCC recurrence and extended the survival rate of tumor-bearing mice." (PMID 41714328, 2026). "ATX suppressed CCL11-driven infiltration of eosinophils into the pancreatic tumor microenvironment to facilitate tumor progression." (PMID 40050933, 2025). "CXCL12 facilitates tumor invasion and metastasis, while CCL11, CXCL14, CCL6, and CCL12 further contribute to chemoresistance and metastasis by enhancing glycolysis." (PMID 40230452, 2025). "CCL11, as a chemokine, plays a role in tumor cell migration, angiogenesis, and the regulation of immune cells." (PMID 40696350, 2025).
tumor (continued). "The NFSA cell line, which is characterized by a high CCL11 expression, exhibited restricted angiogenesis and extensive necrosis, while the MS-K line with minimal CCL11 expression demonstrated robust tumor growth and well-developed vascular networks." (PMID 40429807, 2025). "Tumor-derived CCL11 establishes autocrine signaling loops that enhance malignant cell proliferation and invasive potential." (PMID 40429807, 2025). "Transwell experiment showed that the addition of CCL11 significantly reduced the invasion and migration ability of tumor cells." (PMID 38305920, 2024). "DPP4 modulates chemokines by cleaving CCL11, reducing eosinophil infiltration and T-cell-independent anti-tumour responses." (PMID 39451776, 2024). "This enhanced immunogenicity and antitumor activity of CCL11 was preserved in B16-OVA tumor-bearing mice treated with the identified chemokine fused to the ovalbumin (OVA) antigen." (PMID 38459592, 2024). "CCK-8 and colony formation experiments showed that the proliferation and colony formation of tumor cells were inhibited in vitro after the addition of CCL11." (PMID 38305920, 2024). "Among them, CCL11 showed the strongest anti-tumor enhancing effect, as evidenced by a high percentage of clearance of the large established tumors in multiple repeated experiments which was not shown by previous DNA vaccines." (PMID 38459592, 2024). "Elevated expression of CCL11 by tumor cells, which interacted with CCR5 or CXCR3 receptors on both macrophages and tumor cells, was positively associated with tumor growth." (PMID 39519201, 2024). "IHC staining showed higher CCL11 expression in clinical tumor samples compared to adjacent normal tissues, corroborating TCGA database findings." (PMID 38305920, 2024). "Next, we established control and ATX-deficient tumors, sorted EpCAM+ tumor cells by fluorescence-activated cell sorting (FACS) and measured Ccl11 expression, which was higher in ATX-deficient PDAC cells." (PMID 38195933, 2024). "Statistical analysis based on tumor stage showed significant differences between CCL11 high‐ and low‐expression groups." (PMID 38305920, 2024). "Eosinophil mediators, such as IL-5, IL-33, granulocyte–macrophage colony-stimulating factor (GM-CSF), thymic stromal lymphopoietin (TSLP), and CCL11 also determine eosinophil behavior toward tumor cells." (PMID 37587450, 2023). "The functional role of CCL11 in tumor–stromal signaling, particularly TME-mediated aggressiveness, remains controversial." (PMID 35804913, 2022). "IL‐33, a tumour‐derived alarmin, in solid tumour induces eosinophil migration and promotes CCL11‐mediated eosinophil infiltration and degranulation, which in turn leads to tumour cell cytotoxicity and reduced tumour growth." (PMID 35344301, 2022). "Through CCL11, CAFs interact and crosstalk with cancer cells, eventually leading to tumor progression." (PMID 35804913, 2022). "Immunohistochemical staining of CCL11 was observed in the putative area where CAFs and tumor from a representative case delineated the same area, and distribution of CCR3 investigated in the same area showed that both expressions coexisted." (PMID 35804913, 2022). "Another study identified that CCL11 was primarily expressed by α-SMA+ fibroblasts in the tumor tissue of PC patients and was involved in an enhanced stromal reaction." (PMID 35957897, 2022). "Hollande and colleagues emphasised the role of CCL11 by demonstrating that dipeptidyl peptidase DPP4 (CD26) inhibitor sitagliptin led to enhanced tumor control through enhanced CCL11-mediated eosinophil recruitment at the tumor site." (PMID 35563461, 2022). "GM-CSF and CCL11 (eotaxin 1), which are present in tumor tissue, contribute to the attraction of eosinophils." (PMID 35563461, 2022). "The results of necroptosis influences on the tumor immune microenvironment showed that significantly up-regulated expression levels of chemokines existed in Clusters B and C, such as CCL11, CCR1, CXCL10, and PPBP (upper part)." (PMID 35911707, 2022).
tumor (continued). "In these models, expression of IL-33 in tumors was a key inducer of CCL11 production and eosinophil-mediated anti-tumor responses." (PMID 33757558, 2021). "Earlier studies showed the role of CCL11 in tumor cells migration, tissue invasion and angiogenesis in ovarian cancer." (PMID 33608009, 2021). "Administration of the DPP4 inhibitor resulted in higher concentrations of CCL11 and increased migration of eosinophils into tumor parenchyma, enhancing the eosinophil-mediated anti-tumor responses." (PMID 33614513, 2021). "To overcome this problem, we proposed to exploit this behavior by using three chemoattractants: CXCL10, CCL2 and CCL11, released by a biodegradable hydrogel (GlioGel) to produce a migration of tumor cells toward a therapeutic trap." (PMID 34830041, 2021). "Proliferation of tumor cells was significantly reduced after 72 h arguing for a direct effect of CCL11 on CCR3 that in turn promotes cell proliferation (*p < 0.05)." (PMID 33608009, 2021). "CCL11/Eotaxin-1, by recruiting eosinophils into the neoplastic niche, also has anti-tumor properties." (PMID 33114763, 2020). "Our data indicate that loss of FAK in CAFs from FSPCre−;FAKfl/fl mice increases Ccl6, Ccl11, Ccl12 and pentraxin-3 expression with an enhancement in malignant cell glycolysis and tumour growth." (PMID 32157087, 2020). "The concentrations of five cytokines out of 32 compounds analyzed on the array—IL-7, G-CSF, CCL11, LIF and VEGF—were higher in the tumor-associated adipose tissue than in normal mouse adipose tissue." (PMID 31752313, 2019). "Calcitriol or its analogues downregulated the expression of 4 genes related to the Th1 response in tumour tissue (Ifng (only calcitriol), Socs1, Tbx21 and Fasl) and upregulated 5 genes related to the Th2 response (Ccl11, Ptgdr2, Il9, Asb2 and Il5)." (PMID 31595196, 2019). "Lower levels of CCL11 (Eotaxin-1) and CXCL10 (IP-10) in the tumor tissue were associated with a better prognosis (p = 0.022; p = 0.002)." (PMID 28537901, 2017). "For several solid tumors elevated levels of CCL11 either in the serum or in tumor tissue have been reported." (PMID 28537901, 2017). "Our primary goals were to explore the clinical significance of CCL11/CCR3 in tumor progression, and to find out valuable prognostic and predictive biomarkers in GBM." (PMID 27119233, 2016). "In this study, we first analyzed the cytokine profiles of clinical GBM tissues and discovered that CCL11 was a potential GBM tumor biomarker." (PMID 27119233, 2016). "In anaplastic large cell lymphomas, the CCR3/CCL11 interaction promotes tumor cell proliferation and inhibits apoptosis through ERK1/2, Bcl-xL and the production of survivin." (PMID 25110692, 2014). "Depending on the tumor context, tumor cells, fibroblasts, and endothelial cells in the tumor stroma as well eosinophils themselves have been identified as important sources for CCL11 within the tumor." (PMID 24782982, 2014). "Recruitment of eosinophils to the tumor depends on the chemokine CCL11, which is highly selective for this cell type." (PMID 24782982, 2014). "Additionally, the inhibition of dipeptidyl peptidase-4 (DPP4/CD26) promotes eosinophil infiltration into solid tumors by increasing CCL11 levels, leading to significant suppression of tumor growth." (PMID 40721870, 2025). "Clinically, CCR3 expression in tumor specimens shows a positive correlation with advanced histological grades, suggesting that CCL11/CCR3 signaling may drive tumor progression and metastatic potential in CCR3-positive RCC." (PMID 40429807, 2025). "Similarly, CCL11's contribution to tumour progression through eosinophil recruitment and angiogenesis modulation represents an important mechanistic link in inflammation‐driven carcinogenesis." (PMID 40682474, 2025).
tumor (continued). "Furthermore, tumor-secreted CCL11 exerts paracrine effects on immune cells and modulates the tumor microenvironment, collectively contributing to tumor progression." (PMID 40429807, 2025). "Moreover, levels of CCL11, a chemokine responsible for eosinophil recruitment, infiltration, and degranulation, predicts eosinophil cytotoxicity and tumor response to ICI therapy." (PMID 39267741, 2024). "PCR results showed that CCL11 was significantly highly expressed in tumor tissues." (PMID 38305920, 2024). "Among the stromal genes, we note that the everolimus+SNX631 combination upregulated an angiogenesis inhibitor Tnmd and putative tumor-suppressive proteins Acaca, Per3, and Ccl11, whereas Aldh1a2, a tumor stimulating stromal factor, was downregulated by the combination." (PMID 39541354, 2024). "To assess this relationship in vivo, we stained for CCL11 in control and ATX-deficient tumors and found greater CCL11 expression when ATX was inhibited, either constitutively or inducibly, which was barely detectable in ATX-expressing tumor cells." (PMID 38195933, 2024). "CCL11 expression was elevated in BRCA tumor tissues compared to adjacent normal tissues." (PMID 38305920, 2024). "Furthermore, a cytokine array analysis showed increased Il33 and Cst3 expression in both tumor and serum from KPC-Cdh11+/+ mice compared to KPC-Cdh11+/- mice, while Il11 was highly enriched in KPC-Cdh11+/+ serum alone and Ccl11 was enriched in tumor alone." (PMID 37954069, 2023). "Tumor-secreted CCL11 can recruit eosinophils to tumor cells and inhibit tumor growth." (PMID 37587450, 2023). "Additionally, in a different set of prostate cancer preclinical models, the pharmacologic inhibition of protein kinase D blunted the production of SCF, CCL5, and CCL11 and led to decreased MC migration and reduced tumor growth in vivo." (PMID 37376140, 2023). "Additionally, we verified that CCL11 expression from surrounding CAFs directly affects the tumor behavior and promotes its aggressiveness by targeting CCR3." (PMID 35804913, 2022). "Notably, administration of a DPP4 inhibitor resulted in higher concentrations of the chemokines CCL11, interleukin (IL)-4, IL-5, and IL-33 in tumor extracts and increased migration of eosinophils into solid tumors." (PMID 35053615, 2022). "Thus, IL-33 has dual functions in regulating eosinophil-dependent anti-tumor immunity by upregulating CCL11 expression and stimulating eosinophil degranulation." (PMID 35053615, 2022). "Data from our study and previous reports suggest that increased tumor infiltration of neutrophils induced by cabozantinib might be due to the increased neutrophil-related chemokines CCL11 and CXCL12 in the tumor microenvironment." (PMID 33954115, 2021). "The combination treatment caused increased secretion of CCL2, CCL21, CXCL1, CXCL2, CXCL5, CXCL9 and CXCL16, whereas the levels of CCL11, CCL17, CCL19, CCL22, CCL25, CCL27 and CX3CL1, which are associated with protumourigenic effects, were decreased in the tumours." (PMID 33014356, 2020). "As CCR3 is also expressed on eosinophils and subpopulations of Th2 cells, CCR3+ cells secreting CCL11 and IL-4 may produce a Th2-dominant microenvironment, which is suitable for tumor growth." (PMID 29915722, 2018). "The adverse prognosis related to CCL11 levels in patients’ serum in this study might be explained by the fact that the expression in serum and tumor tissue is unrelated and highly-dependent on the immunogenic factors." (PMID 28537901, 2017). "Different expression profiles depending on the tissue type might be responsible for the adverse prognostic CCL11-levels in the tumor tissue." (PMID 28537901, 2017). "Higher serum levels of CCL11 might induce higher immunogenic response to the tumor tissue leading to better clinical outcome." (PMID 28537901, 2017).